RND3 (Rho family GTPase 3)
Diseases named in the same sentence as RND3 in open-access papers (continued):
Sharing a sentence is not in itself a finding about the gene and the disease.
tumor (continued). "Next, we selected several EZH2 or LSD1 potential targets (P15, P21, KLF2, PTEN, TFPI2, LATS2, E-cadherin, and RND3) with tumor-suppressive role, and hypothesized that some of which may be associated with AGAP2-AS1-mediated carcinogenicity." (PMID 31186379, 2019). "Furthermore, the expression levels of miR-802, LIMCH1, and Rnd3 were assessed in A549 cells and mice flank tumor tissues." (PMID 27144337, 2016). "RND3 was found in the cytoplasm of tumor cells but also in the nucleus." (PMID 26132659, 2015). "The assessment of RND3 expression levels in GBM patients could be a new reference biomarker for tumor growth and patient prognosis." (PMID 26108681, 2015). "Previous publications have demonstrated that up-regulated miR-17-5p and miR-20a-5p could promoted cell proliferation, tumour growth and cell cycle progression by targeting the RND3 and BIM tumour suppressor gene, respectively." (PMID 26462034, 2015). "Expression of Rnd3 express was precisely regulated in human tumor tissues." (PMID 25372032, 2014). "The atypical Rho protein Rnd3/Rho8/RhoE is an important regulator of migration of fibroblasts and tumor cells that acts by inhibiting RhoA through stimulation of the Rho GTPase-activating protein p190RhoGAP, and/or inhibition of the activity of ROCKI, one of the main effectors of RhoA." (PMID 21435554, 2011). "In the M6A-dependent pathway, VIRMA regulates key oncogenes (e.g., FOXM1, HK2) and tumor suppressor genes (e.g., RND3, BTG2), affecting the proliferation, metastasis, metabolic reprogramming, and drug resistance of tumor cells." (PMID 40723784, 2025). "They then performed Rnd3 staining on HCC slices and found that entotic cells were present in tumour sections with low Rnd3 expression." (PMID 38429285, 2024). "In lymph node metastases compared to the invasive front of the tumor, ONECUT2 and SOX2 were down-regulated, while PTPN13, TGFB2, ZEB2, RND3 and CDKN1B were up-regulated." (PMID 34046357, 2021). "After verification by The Cancer Genome Atlas (TCGA) and Clinical Proteomic Tumor Analysis Consortium (CPTAC) databases, RND3 was finally chosen." (PMID 34050132, 2021). "Accordingly, in tumour and adjacent normal tissues from 202 patients with CRC, including 80 nodal metastases, Rnd3 expression using immunohistochemistry was analysed." (PMID 31623346, 2019). "We therefore reverse engineered a static ARACNE mutual information network representing the neighbourhood of RND3, RHOC, RHOBTB1 and RHOBTB2 during the tumour implantation time course." (PMID 26132659, 2015). "Furthermore, RND3 CNV correlates to its expression and is predictive of survival, suggesting that changes in the activity of this particular Rho GTPase could be an early event associated to transformation and tumour progression." (PMID 26132659, 2015). "To confirm the inverse correlation between RND3 protein expression levels and GBM tumor growth, we detected phosphorylated histone 3 (p-His3) levels, a cell proliferation marker, in GBM and human normal brain tissues by western blot analysis." (PMID 26108681, 2015). "Rnd3 is an inhibitor of ROCK-I and evidence has been reported that it can play a role in controlling morphology and invasion of rounded tumor cells." (PMID 21209796, 2010). "An increasing number of studies have demonstrated that various tumor suppressors can be substrate proteins in the CMA pathway, including mainly p73, N-CoR, PED, and RND3, among others, and that the procancer effects of CMA are achieved by degrading these tumor suppressors." (PMID 37509689, 2023). "Next, we selected several EZH2 or LSD1 potential targets (P15, P21, KLF2, PTEN, KLF2, LATS2, RND3, and NKD2) with tumor-suppressive role, and hypothesized that some of which might be associated with LINC00665-mediated carcinogenicity." (PMID 34094920, 2021).
tumor (continued). "All of the eight GBM tissues displayed higher expression levels of HES5 mRNA along with lower levels of RND3 mRNA compared to the corresponding tumor ABTs, indicating a strong negative correlation between RND3 expression and HES5 transcript levels." (PMID 26108681, 2015). "In these mice, both cell lines developed tumors, which showed similar growth rates, indicating that Rnd3 does not affect subcutaneous tumor growth." (PMID 21209796, 2010). "This implies that ASCL1’s role in conferring tumor cell migration within GBMs may utilize downstream mechanisms independent of RND3 function." (PMID 39609428, 2024). "Furthermore, as reported in other tumors types, upregulation of DAB2, RND3, TMEM97, CSE1L, MYO1C, and PTPRK have been shown to suppress or functionally redistribute E-cadherin expression in cancer cells, resulting in EMT, increased invasion, advanced tumor stage and poor patient survival." (PMID 27863424, 2016). "In the analysis of human GBM biopsies, we detected significant declines in RND3 transcript and protein levels in GBM tissues compared to normal human brain tissues and even in the corresponding tumor ABTs." (PMID 26108681, 2015).
cancer (40 papers, 2010 to 2026). A tumor composed of atypical neoplastic, often pleomorphic cells that invade other tissues. "Rnd3 regulates cellular processes commonly dysregulated in cancer, and altered Rnd3 expression has been linked to several cancer types." (PMID 41735013, 2026). "Rnd3/RhoE has been implicated in cancer cell motility and its mRNA and protein expression can be upregulated by DNA damage-inducing stimuli." (PMID 38297314, 2024). "High expression of Lamp2A was correlated with reduced RND3 protein levels in cancer gastric cells, and the silencing of Lamp2A was associated with increased RND3 protein levels and inhibited cell proliferation." (PMID 33643916, 2020). "Meanwhile in cancers, down-regulation of Rnd3 is closely associated with invasion and metastasis." (PMID 25372032, 2014). "Conversely, CSRNP1, RND3, and RCAN1 were significantly downregulated, each linked to anti-proliferative or prognostic roles in cancer." (PMID 41216224, 2025). "While miR-200b-induced CDKN1B degradation promotes cancer cell proliferation, reduced expression of miR-200b was accompanied by an increased expression of RND3, an important regulator of cell migration." (PMID 36140249, 2022). "Thus, the genes LOXL3, ADAM19, FBN2, and RND3 are associated with cancer relevant biological processes such as loss of adhesion, proliferation, migration and metastasis and are therefore might be functionally related to CLIP2 in the context of radiation induced PTC-carcinogenesis of PTC." (PMID 32727620, 2020). "That cancer history is contradictory, as with other genes, with reports indicating a potential for high RND3 expression representing both pro- and anti-cancer results." (PMID 30962767, 2019). "A recent review regarding RND3 specifically evaluated the pro- and anti-cancer functions and concluded that indeed, the overall impact of RND3 is context dependent." (PMID 30962767, 2019). "The role of Rnd3 in inhibiting the proliferation of these two NSCLCs makes it a possible target for cancer treatment." (PMID 25372032, 2014). "Rnd3 has been shown to regulate cell morphology and migration in cultured fibroblasts and cancer cells by antagonizing RhoA." (PMID 21435554, 2011). "Rnd3 is involved in actin organization, as well as the development of cancers." (PMID 27144337, 2016). "Rnd3 seems to regulate cancer cell invasion mainly through its effects on RhoA/ROCK activity." (PMID 25705175, 2015). "Recently, studies have emphasized the critical role of Rnd3 in different types of cancer." (PMID 25372032, 2014). "Recently, studies have reported the broad function of Rnd3 in cancer and neuron system development." (PMID 25372032, 2014). "Interestingly, Rnd3 differentially expresses in various types of cancer." (PMID 28881704, 2017). "Thus, finding the natural products to reduce the degradation of Rnd3 through CMA as a treatment for cancer may evolve over the next several years." (PMID 28881704, 2017). "However, the specific contribution of Rnd3 to cancer cell invasion is controversial, since it has been shown to both promote and inhibit invasion, suggesting that Rnd3 may act via more than one molecular mechanism." (PMID 25705175, 2015). "CMA may aid cancer proliferation by the degradation of the inhibitors of cell proliferation, such as Rho-related GTP binding protein RhoE (RND3], and pro-apoptotic protein Bcl-2-binding component 3 (BBC3)." (PMID 35887082, 2022). "Our manuscript highlights the potential of circ_0008234, miR-574-5p, and RND3 as novel therapeutic targets for treating LUAC patients and may help to further explore the specific mechanism of the ceRNA network in cancer." (PMID 34050132, 2021). "Indeed, Rnd proteins, especially Rnd3, have been shown to also control the migration of non-neuronal cell types, such as epithelial cells or cancer cells." (PMID 25705175, 2015).
infection (6 papers, 2015 to 2026). The state of being infected such as from the introduction of a foreign agent such as serum, vaccine, antigenic substance or organism. "Rnd3 expression was overtly elevated in AAV9-Nr1H2-infected HFD-STZ-treated mouse hearts compared with AAV9-scramble-infection in HFD-STZ mice." (PMID 36438502, 2022).
cardiovascular diseases (4 papers, 2021 to 2025). "Rnd3 is a small Rho-GTPase that has been implicated in various cardiovascular diseases." (PMID 40025898, 2025). "Abnormal expression of RND3 may be the main cause of some cardiovascular diseases." (PMID 33953793, 2021). "Emerging evidence has suggested a link between Rnd3 expression and hallmarks of cardiovascular disease progression, such as vascular remodeling in hypertension, developmental arrhythmogenesis, and inflammatory responses in myocardial infarction 10-13." (PMID 36438502, 2022). "Importantly, emerging evidence has demonstrated that Rnd3 overexpression effectively improves myocardial structure and function, providing a promising therapeutic avenue for the management of cardiovascular diseases." (PMID 39755713, 2025). "Emerging evidence suggests a link between Rnd3 expression and onset of cardiovascular diseases." (PMID 36438502, 2022).
neurodegenerative disease (3 papers, 2018 to 2023). A disorder of the central nervous system characterized by gradual and progressive loss of neural tissue and neurologic function. "Altogether, our results demonstrate that Rnd3 is relevant to maintain mitochondria function, suggesting a possible relationship with neurodegenerative diseases." (PMID 35832788, 2022). "Rnd3 has been demonstrated to be an essential protein in the CNS development and suggested to be involved in some neurodegenerative diseases." (PMID 35832788, 2022). "Further studies will be needed to clarify the actual role of Rnd3 in mitochondria metabolism and its relationship with neurodegenerative diseases." (PMID 35832788, 2022). "Our results suggest that Rnd3 is relevant for mitochondrial metabolism and could be involved in the onset or progression of some neurodegenerative diseases." (PMID 35832788, 2022). "Recent research found a decreased rate of brain apoptosis in Rnd3-knockout mice and that the regulation of central nervous system apoptosis, via the RND3-NF-κB P65 signaling pathway, may be an alternative approach for the treatment of neurodegenerative diseases." (PMID 36875640, 2023).
cardiac diseases (2 papers, 2021 to 2022). "Considering that restored level of Rnd3 serves as a protective mechanism in heart diseases, development of medications to jack up Rnd3 signaling may be a promising therapeutic approach for DCM and associated cardiac diseases." (PMID 36438502, 2022).
adenocarcinoma (1 paper, 2022). A common cancer characterized by the presence of malignant glandular cells. "Similarly, Rho family GTPase 3 (RND3) has also been recognized as a downstream target of miR-574-5p, the inhibition of which significantly accelerated apoptosis and suppressed adenocarcinoma progression." (PMID 36671425, 2022).
hematological neoplasm (1 paper, 2023). "However, the possible role of Rnd3 in hematological neoplasm remains unknown, so our investigation aims to determine the potential role of Rnd3 in MM." (PMID 37143063, 2023).
neurodevelopmental disorder (1 paper, 2025). A behavioral and cognitive disorder with onset during the developmental period that involves impaired or aberrant development of intellectual, motor, or social functions. "Understanding Rnd3’s function in this neurogenic niche could provide insights into mechanisms regulating neuroblast behavior and their implications in neurodevelopmental disorders." (PMID 40625683, 2025).
neurological disorders (1 paper, 2011). "This is the first model to study the in vivo functions of a member of the Rnd subfamily of proteins, revealing the important role of Rnd3/RhoE in the normal development and suggesting the possible involvement of this protein in neurological disorders." (PMID 21552537, 2011).
RND3 also shares sentences with these, for which no sentence is quoted: alveolar rhabdomyosarcoma (2 papers); cervical cancer (2); colon cancer (2); mesenchymal tumor (2); thyroid cancer (2); brain tumor (1); breast adenocarcinoma (1); chronic leukemia (1); Cirrhosis (1); HIV-1 infection (1); lymph node metastases (1); malaria (1); MALT lymphoma (1); metastatic melanoma (1); obstructive hydrocephalus (1); pancreatic cancer (1); papilloma (1); type 2 diabetes mellitus (1); viral infection (1).